EPB41L5 (erythrocyte membrane protein band 4.1 like 5)
Description:
Plays a role in the formation and organization of tight junctions during the establishment of polarity in epithelial cells.
Synonyms: KIAA1548; FLJ12957; BE37; YMO1; YRT; LULU; LULU1
Tractability: Antibody: UniProt places it where antibodies can reach, with high confidence; its Gene Ontology location is reachable by antibodies, with high confidence; the Human Protein Atlas places it where antibodies can reach. PROTAC: ubiquitination databases record sites on it; its protein half-life has been measured.
Gene: Protein-coding gene on chromosome 2 (120,013,066 to 120,179,119, forward strand). Ensembl gene ENSG00000115109.
Subcellular location: Cytoplasm; Cell junction, adherens junction; Cell membrane; Photoreceptor inner segment
Subcellular location (Human Protein Atlas): Plasma membrane
Pathways (Reactome):
Neuronal System: Neurexins and neuroligins
Gene Ontology:
Molecular function: protein binding; cytoskeletal protein binding; protein domain specific binding
Biological process: actomyosin structure organization; epithelial to mesenchymal transition
Cellular component: plasma membrane; cytoplasm; cytoskeleton; cytosol; photoreceptor inner segment; adherens junction; cell leading edge; focal adhesion; ruffle membrane
Genetic constraint (gnomAD): Loss-of-function variants: 30 observed, 66.83 expected, observed/expected ratio (o/e) 0.45, 90% interval 0.34 to 0.61. The upper end of that interval is the gene's LOEUF score, 0.61, which puts it in group 2 of 6, group 1 being the genes least tolerant of losing a copy. Missense variants: 608 observed, 678 expected, observed/expected ratio (o/e) 0.9, 90% interval 0.84 to 0.96. Synonymous variants: 220 observed, 237.8 expected, observed/expected ratio (o/e) 0.93, 90% interval 0.83 to 1.03.
Homologues: Orthologues: chimpanzee EPB41L5 (99% identical), macaque EPB41L5 (98% identical), dog EPB41L5 (87% identical), pig EPB41L5 (86% identical), rabbit EPB41L5 (85% identical), mouse Epb41l5 (84% identical), rat Epb41l5 (84% identical), guinea pig EPB41L5 (82% identical), tropical clawed frog epb41l5 (64% identical), zebrafish epb41l5 (48% identical), Drosophila melanogaster yrt (42% identical), Caenorhabditis elegans frm-2 (33% identical), and 2 more. Paralogues in human: EPB41L4B (48% identical), EPB41L4A (28% identical), EPB41L3 (28% identical), EPB41L2 (27% identical), EPB41 (26% identical), EPB41L1 (25% identical), FRMD3 (23% identical), FRMD5 (22% identical), MYLIP (15% identical), FRMD6 (14% identical).